PRLR (prolactin receptor)
Diseases named in the same sentence as PRLR in open-access papers (continued):
Sharing a sentence is not in itself a finding about the gene and the disease.
breast cancer (continued). "Herein we describe the characteristics and functional attributes of ABBV-176, a novel pyrrolobenzodiazepine (PBD) ADC targeting PRLR across multiple breast cancer models including low PRLR models and models insensitive to MMAE (monomethyl auristatin)-based PRLR ADCs." (PMID 34107902, 2021). "Interestingly, endogenous PRL induces ER responsiveness and enhances PRLR expression/transcription resulting in proliferation of breast cancer cells." (PMID 34572912, 2021). "We hypothesized that the fusion protein MICA-G129R will bridge NK cells and PRLR-positive breast cancer cells." (PMID 34077462, 2021). "Altogether, the PRL/PRLR pathway being a major mammary terminal differentiation pathway, able to drive differentiation of breast cancer cells can thus be proposed as a potential therapeutic target in breast cancer." (PMID 33446633, 2021). "Previous work has shown systemic knockdown of the long form prolactin receptor (LFPRLR) in vivo markedly reduced metastasis in mouse models of breast cancer, but whether this translated to prolonged survival was unknown." (PMID 34375938, 2021). "We hypothesize that the MICA portion of the fusion protein binds to NKG2D to activate NK cells and the G129R portion binds to PRLR on breast cancer cells, so that the activated NK cells will kill the PRLR-positive breast cancer cells." (PMID 34077462, 2021). "In contrast a potent PRLR antibody-drug conjugate (ADC) may provide improved therapeutic outcomes extending beyond either PRLR overexpressing or estradiol-insensitive breast cancer populations." (PMID 34107902, 2021). "Moreover, studies examining large cohorts of human breast cancer cases defined PRLR and PRL as markers of favorable clinicopathological parameters (tumor differentiation) and better patient survival outcomes." (PMID 33446633, 2021). "Instead of sending promoting signals, binding of G129R to PRLR blocks the signal transduction and induces apoptosis in breast cancer cells, and prolonged treatment with G129R induces the accumulation of redundant autolysosomes in 3D cancer spheroids, resulting in autophagy-related cell death." (PMID 34077462, 2021). "These interconnected downstream signaling pathways activated by EGFR/HER2 and PRLR cooperation may enhance proliferation, survival, migration, and invasiveness of breast cancer cells." (PMID 34572912, 2021). "Notably, it has been recently reported that the intermediate isoform of the PRLR, which can hetero-dimerize with the long isoform, acts as a proto-oncogene in breast cancer." (PMID 34071395, 2021). "Activation of PRLR promotes mammary tumor development in transgenic mice overexpressing PRL gene." (PMID 34572912, 2021). "In addition to the role of the predominant long form of PRLR in breast cancer, recently it has been shown that the human intermediate PRLR (alternatively spliced isoform) is a mammary proto-oncogene capable of stimulating cell survival and proliferation." (PMID 34572912, 2021). "The PRL/PRLR pathway has been studied for decades because of its etiological role in breast cancer." (PMID 34077462, 2021). "In addition, knocking down the long PRLR gene can inhibit breast cancer's metastasis in the lung and liver, indicating that the long PRLR gene plays a crucial role in breast cancer metastasis." (PMID 34651424, 2021). "Interestingly, our results showed that suppression of PRLR expression promoted tumor cellular plasticity and tumorigenicity in both breast cancer subtypes." (PMID 33446633, 2021). "Notably, while loss of PRLR enhanced the tumorigenic and metastatic potential of both HR+ and HER2-E breast cancer cells, these effects appear to be mediated through distinct mechanisms." (PMID 33446633, 2021). "The T-47D cells incubated with MICA-G129R conditioned media showed strong green fluorescence, while the cells with control conditioned media did not, demonstrating that the fusion protein MICA-G129R in the conditioned media binds to PRLR-positive breast cancer T-47D cells." (PMID 34077462, 2021).
breast cancer (continued). "Having shown that loss of PRLR expression in both HR+ and HER2-E breast cancer cells augmented their aggressive phenotype, we next investigated whether it could also modulate their differentiation state." (PMID 33446633, 2021). "In conclusion, a novel fusion protein MICA-G129R was created and demonstrated able to bind to PRLR-positive breast cancer cells and NK cells, promote the release of granzyme B and IFN-γ by NK cells and enhance the cytotoxicity to PRLR-positive breast cancer cells." (PMID 34077462, 2021). "Although the levels of PRLR RNA in these cell lines was generally much lower than observed for many breast cancer cell lines, several cell lines including ovarian, endometrial, prostate and colorectal cell lines were sensitive to killing by ABBV-176, but not h16f-MMAE." (PMID 34107902, 2021). "Consistent with the total protein levels, when the RNA seq data was compared to TCGA breast cancer data, most of these models expressed low levels of PRLR relative to patient samples, implying that these models express PRLR equal to, or lower than, most breast cancer (BrCa) patient tumors." (PMID 34107902, 2021). "Although PRLR expression has generally been primarily associated with breast cancers, additional evaluation of the efficacy of ABBV-176 in non-breast cancer indications that express low levels of PRLR may be warranted." (PMID 34107902, 2021). "PRLR is overexpressed in certain types of breast cancer as well as prostate cancer." (PMID 32398042, 2020). "It’s confirmed that prolactin receptor plays an important role in the development of breast cancer." (PMID 32398042, 2020). "In addition, an anti-PRLR antibody-drug conjugate (ADC) had significant PRLR-specific antitumor activity against breast cancer, and bispecific antibody-ADCs bridging HER2 and PRLR improved efficacy of HER2 ADCs." (PMID 32398042, 2020). "Additionally, the development of prolactin receptor blocking agents have so far proved ineffective for breast cancer treatment." (PMID 32831062, 2020). "PRLR-DbsAb in vitro could recruit and activate T cells to promote the release of Th1 cytokines IFN- γ and TNF- α, which could kill PRLR expressed breast cancer cells." (PMID 32398042, 2020). "PRLR is an independent predictor of better outcomes in patients with breast cancer." (PMID 33392181, 2020). "PRLR is one kind of type I cytokine receptors highly expressed in breast cancer cells." (PMID 32398042, 2020). "Because AKT is rapidly repressed in response to C75-induced blockade of FASN activity, our findings suggest a positive feedback regulation between FASN and autocrine prolactin expression via AKT-driven activation of the PRLR/JAK/STAT5 pathways in PR+ breast cancer cells." (PMID 33335078, 2020). "In this case, the combined use of PRLR or GHR inhibitors may produce better anti-breast cancer potential than PRLR or GHR inhibitors alone." (PMID 33362552, 2020). "We next compared the expression level of the gene signature of PRLR/TGFβRI/TGFβRII generated above in relation to estrogen receptor (ER) expression, as well as in relation to the different breast cancer molecular subtypes using clinical cases available from the GOBO database." (PMID 30987013, 2019). "We initiated studies to determine whether endogenous PRL action in breast cancer cells is required for E2 induced increase in PRLR gene expression." (PMID 28423697, 2017). "Emerging evidence suggests that targeting the PRLR signaling pathway may represent a novel antihormonal approach for the treatment of breast cancer." (PMID 29262565, 2017). "Targeting CDK7 kinase, which is known to regulate both transcription and the cell cycle and ERα phosphorylation with the THZ1 inhibitor was found to effectively inhibit the transcription of the PRLR and its contribution to cell migration induced E2/ERα in breast cancer cells." (PMID 28423697, 2017).
breast cancer (continued). "Therefore, there are reproducible associations, in humans, of increased breast cancer risk, progression, metastases and treatment resistance with increased PRL and the PRLR." (PMID 27782069, 2016). "Constitutively-active PRLR variants have been identified, although not in association with breast cancer." (PMID 27782069, 2016). "Our studies suggest that disrupting PRLR-focal adhesion signals may point to novel therapeutic targets in aggressive ERα+ breast cancers." (PMID 27344177, 2016). "We next analyzed PRLR gene expression levels in different breast cancer molecular subtypes including TNBC (660 patients), Her-2 (170 patients), luminal A (703 patients) and luminal B (170 patients) using robust single sample predictor classification (RSSPC) in bc-GenExMiner 3.0 database." (PMID 27480353, 2016). "Furthermore, PRLR can be used as a predictive marker for the possible use of PRL as a pro-differentiation therapy in breast cancer." (PMID 27480353, 2016). "The MCF-7 and T-47D breast cancer cell lines overexpressing PRLR were used." (PMID 26346346, 2015). "Although JAK2/STAT5 represents the principal physiological pathway of PRLR’s action, the signaling to SFKs by this receptor could also play a role in breast cancer progression." (PMID 26733941, 2015). "Transgenic rodents overexpressing PRLR in the breast develop mammary tumors with a high frequency." (PMID 26733941, 2015). "It is currently unclear whether PRL/PRLR signaling may turn into modifications that have an impact on breast cancer cell movement and possibly metastasis through the control of actin cytoskeleton rearrangement." (PMID 26733941, 2015). "PRL effects on breast cancer are mediated by interaction with its receptor (PRLR), a member of the cytokine receptor superfamily, characterized by a tripartite structure: an extracellular ligand-binding domain, a short transmembrane domain, and an intracellular domain." (PMID 26733941, 2015). "Prolactin receptor is found in up to 80% of breast cancer cells, where it couples to several signaling pathways, including Janus Kinase (JAK)-2/Signal Transducer and Activator of Transcription (STAT)-5, mitogen-activated protein kinase (MAPK), and phosphatidylinositol-3-OH-kinase (PI3K)." (PMID 26733941, 2015). "In this study, we have shown that in breast cancer cells, regulation of PRLR gene expression at the transcriptional level by its own ligand, independent of E2, can take place with the essential participation of the JAK2/STAT5 and mitogen-activated protein kinase (MAPK) signaling pathways." (PMID 25193864, 2014). "Taken together, our studies have demonstrated an increase in expression of PRLR receptors in breast cancer cells induced by endogenous PRL/PRLR action via STAT5 interaction with pERα and complex formation with Sp1/C/EBPβ at the PRLR promoter in the absence of estrogen." (PMID 25193864, 2014). "We cannot exclude that PRLR signaling is still capable of promoting breast cancer progression and invasion through Jak2/Stat5-independent pathways such as c-Src, FAK, and MAP kinases and beyond towards proliferative effects; thus, other PLR roles are currently being diligently investigated." (PMID 24148306, 2013). "Furthermore, 70-95% of human breast cancers express PRL receptor (PRLR), and many breast cancer cell lines express high levels of PRLR with evidence of proliferative or survival responses to PRL in vitro." (PMID 23758962, 2013). "Another report showed a low ratio of short to long PRLR forms in breast cancer tumors when compared with normal samples; this reduced expression in patients with cancer could contribute to breast tumor development and progression." (PMID 24148306, 2013). "Previous reports have proposed a mechanism by which PRLR might become stabilized and accumulated in breast cancers." (PMID 24148306, 2013).
breast cancer (continued). "Future studies are warranted to determine if multifactorial convergences of the PRLR/STAT5, EGFR, and RANK/RANKL pathways may contribute to breast cancer risk." (PMID 23938070, 2013). "Findings presented here identify PRLR/STAT5, EGFR, and RANK/RANKL as molecular pathways that may be relevant to increased breast tissue proliferation, mammographic density, and breast cancer risk in postmenopausal women taking EPT." (PMID 23938070, 2013). "Long (90 kDa) and short (42 kDa) PRLr isoforms resulting from differential splicing and an intermediate isoform (65 kDa) from an in-frame truncation have been previously reported in other cell lineages, including human mammary tumor." (PMID 23731754, 2013). "Previous studies had suggested that in some subgroups of breast cancer patients, detection of PRLR may have prognostic significance." (PMID 21144038, 2010). "Since these antibodies are specifically directed against each PRLR isoform, they are valuable tools for the evaluation of breast cancer PRLR content and have potential clinical importance in treatment of this disease by providing new reagents to study the protein expression of the human PRLR." (PMID 21144038, 2010). "Obviously more samples, with attendant clinical information, would need to be examined for statistical validation and to determine whether PRLR SF expression could be routinely used to distinguish between the breast cancer subtypes." (PMID 21144038, 2010). "We found differences in expression levels for the PRLR isoforms in lobular vs. ductal carcinomas that demonstrate these antibodies may be used as a new clinical tool to distinguish between subclasses of breast cancer." (PMID 21144038, 2010). "In order to determine whether the PRLR isoform expression pattern could aid in identification of breast cancer subtype, we examined 144 ductal and 104 lobular carcinoma biopsies available on tissue arrays with limited clinical information." (PMID 21144038, 2010). "Coexpression of the PRLR in breast cancer cells suggests that such prolactin may act in an autocrine/paracrine fashion to influence cell growth and survival." (PMID 18681966, 2008). "Furthermore, the majority of human breast cancers have been shown to express the prolactin receptor (PRLR)." (PMID 18681966, 2008). "The changes seen in this study in the reciprocal STAT5a/PRLR relationship with breast carcinoma may be due to signaling defects in this pathway." (PMID 21655368, 2008). "A total of 33 and 60 haplotype "tag" SNPs (tagSNPs) that allowed for high predictability (Rh2 ≥ 0.70) of the common haplotypes in PRL and PRLR, respectively, were then genotyped in a multiethnic breast cancer case-control study of 1,615 invasive breast cancer cases and 1,962 controls in the MEC." (PMID 18053149, 2007). "In contrast to a recent study of PRL and PRLR in relation to breast cancer, we observed no strongly significant associations with breast cancer risk." (PMID 18053149, 2007). "No haplotypes in PRL or PRLR haplotypes were significantly associated with breast cancer risk using our type I error criteria (p < 0.0005)." (PMID 18053149, 2007). "Also, PRL/PRLR is expressed in 95% of mammary tumors and 60% of male breast carcinomas." (PMID 40160874, 2025). "Having shown that PRL/PRLR pathway regulates Hippo/YAP pathway in breast cancer cells, we next wished to determine whether PRL signaling also exerts a regulatory role on the Hippo pathway in MECs and whether this regulation is linked to PRL-mediated mammary acini morphogenesis." (PMID 40157909, 2025). "However, to the best of our knowledge, no identified PRLR variants have been shown to differentially impact breast cancer prognosis across treatment modalities." (PMID 40723262, 2025). "Notably, our study provides evidence that inducing and/or maintaining PRL/PRLR signaling is critical in restricting and suppressing breast tumorigenesis and promoting its differentiation function may hold therapeutic value in breast cancer." (PMID 40157909, 2025).
breast cancer (continued). "Our study preliminarily found that tamoxifen could upregulate PRLR level in breast cancer cells." (PMID 38898487, 2024). "On the whole, activation of JAK2-STAT3 and JAK2-STAT5 downstream of IL-6R and PRLR, respectively, may play a coordinated role in the development and progression of luminal breast cancer, suggesting the importance of these signaling cascades in ER-positive breast tumors." (PMID 37834225, 2023). "Although the precise role of PRL-mediated PRL receptor (PRLR) signaling is still controversial in breast cancer cells, PRLR activation seems to be important in tumor initiation, whereas its inhibition may mitigate aggressiveness and/or dissemination of stablished tumors." (PMID 37208719, 2023). "Moreover, in RNA-seq data of breast cancer patients, PRLR expression correlated negatively with the mRNA levels of a number of genes (including Aurkb, Ccna2, Scrn1, Npy, Atp7b and Chaf1b) that are related to stemness, resistance to therapy and poor patient outcome." (PMID 36157462, 2022). "Hence, PRLR signaling has emerged as a relevant target in breast cancer." (PMID 36187116, 2022). "However, in subsequent study these SNPs in the PRLR gene were found not to be associated with breast cancer and multiple fibroadenoma." (PMID 36187116, 2022). "On the basis of our observations and the recognized cooperative interactions between PRL and ER signaling in breast cancer, we hypothesized that inadequacy of the PRL/PRLR signaling axis is a major contributing cause of the poor human-in-mouse engraftment rates of ER+ PDX models." (PMID 34524841, 2021). "In addition, CAML is essential in the growth of PRL/PRLR‐dependent breast cancer cells." (PMID 34651424, 2021). "Collectively the efficacy and safety profile of ABBV-176 suggest it may be an effective therapy across a broad range of breast cancers and other cancer types where PRLR is expressed with the potential to combine with other therapeutics including PARP inhibitors." (PMID 34107902, 2021). "Interestingly, these mammary tumors exhibited low expression levels of PRLR as well as other luminal and epithelial differentiation markers such as (Elf5, Muc1), claudins, and cell adhesion markers (Cdh1, Ocln), while showing elevated levels of EMT and BCSC markers." (PMID 33446633, 2021). "This study indicates that H53 exhibits potential biological activity against breast tumors, which implies that internal image anti-idiotypic antibodies may be a useful strategy for the development of PRLR/GHR dual-function antagonists for breast cancer therapy." (PMID 33362552, 2020). "Similarly, prolactin blockade in epithelial-like breast cancer cells has been shown to induce mesenchymal-like phenotypic changes and enhance invasiveness, whereas activation of PRLR in mesenchymal-like breast cancer cells suppresses mesenchymal properties and reduces invasive behaviors." (PMID 33335078, 2020). "As a result, PRLR-DbsAb could be a new treatment for breast cancer." (PMID 32398042, 2020). "However, how the close functioning of the progesterone/PR and prolactin/PRLR signaling axes that drive the lactogenic/lipogenic phenotypic outcomes in normal mammary gland might be altered in breast cancer tissues remains largely unexplored." (PMID 33335078, 2020). "Our results lead us to propose that the PR isoform-specific regulation of distinct regulatory responses in the cross-talk between prolactin and FASN might be involved in the diverse phenotypic outcomes arising from the prolactin/PRLR signaling axis in luminal breast cancer." (PMID 33335078, 2020). "In addition, an integrin-PRLR cross-talk has recently been described in breast cancer cells." (PMID 24257371, 2013). "In addition to reproductive and environmental factors, genetic variation in the prolactin (PRL) and prolactin receptor (PRLR) genes may be associated with increased prolactin levels and breast cancer risk." (PMID 21470416, 2011).